CCND1 (cyclin D1)
Diseases named in the same sentence as CCND1 in open-access papers (continued):
Sharing a sentence is not in itself a finding about the gene and the disease.
tumor (continued). "In addition, how Ambra1 affects cyclin D1 expression, migration, invasion, and apoptosis in tumor cells through autophagy and the molecular mechanism by which Ambra1 regulates cyclin D1 expression are not clear." (PMID 37225761, 2023). "It is possible that various forms of primary clonal damage may secondarily lead to the dysregulation of cyclin D1, thus providing alternative pathways for cells to develop similar tumor characteristics." (PMID 37427143, 2023). "NF-κB induces cytokines, adhesion molecules and angiogenic factors to be expressed at the tumor site, increasing survival and proliferation of neoplastic cells via regulation of genes related to cell-cycle control (e.g., cyclin-D1, c-MYC) and apoptosis (e.g., BCL-2, cFLIP)." (PMID 36614308, 2023). "Furthermore, pcDNA3.1-mediated overexpression of CCAT2 in MCF-7 cells significantly inhibited the tumor growth in vivo, decreased the levels of Ki67 and CCND1 and suppressed the expression of stemness genes." (PMID 36672487, 2023). "Moreover, several genes from the G2M downregulated gene set, including MKI67, MCM2, CCND1, and their STRING-interacting genes MECOM, TYMS, and MTHFR, are associated with neoplasms." (PMID 37958729, 2023). "IHC analysis of the tumor sections indicated significant reduction in Ki67 and cyclin D1 positive tumor cells in the chemopreventive-agent-treated groups when compared to control group tumors, indicating tumor efficacy is partly driven by suppression of tumor cell proliferation." (PMID 37568816, 2023). "In addition, sorafenib reduces the production of cyclin D1 and arrests the cell cycle to prevent the proliferation of tumour cells." (PMID 38414954, 2023). "Finally, we verified TAX evidently inhibited the tumor growth in nude mice and decreased the expression of c-Myc, cyclin D1, p-AKT and FGFR2 in xenograft tumor." (PMID 37567936, 2023). "A causative role for the resulting cyclin D1 overexpression in tumorigenesis was supported by findings from mouse models in which tissue‐specific promoter‐driven transgenic expression of cyclin D1 led to a high frequency of tumor formation in the corresponding tissue." (PMID 37718413, 2023). "CCND1 tumour expression was not statistically significantly associated with risk of recurrence in NMIBC patients from the UROMOL cohort (HR = 0.96 (95% CI 0.89,1.04), P = 0.35)." (PMID 38994482, 2023). "In addition, patients with recurrent tumors expressed a significantly highermean tumoral p63, and tumoral cyclin D1 when compared with primary tumor patients." (PMID 36716784, 2023). "Further analysis proved that DACH1 inhibited the transcription of cyclin D1 and cyclin A by directly binding to its corresponding promoter region, thereby further repressing the proliferation of cells and tumor growth in various cancer types, such as BC and renal cancer." (PMID 36750914, 2023). "Moreover, CCND1/cyclin D1 up-regulation favors the growth and development of the primary tumor; therefore, it is considered as the proto-oncogene." (PMID 36674631, 2023). "Secondly, a true association between tumour expression of CCND1 and RFS could have been masked by the presence of interaction effects between CCND1 and other genes." (PMID 38994482, 2023). "Cyclin D1, which is related to tumor cell proliferation, also decreases with STAT3 inhibition." (PMID 37369757, 2023). "The p16 protein (also known as p16INK4a), encoded by the cyclin-dependent kinase inhibitor 2A (CDKN2A) gene, is a tumor suppressor, inhibiting cyclin-dependent kinases (CDK4/6) that maintain Rb in a phosphorylated state when bound to cyclin D1 (encoded by CCND1)." (PMID 37109525, 2023).
tumor (continued). "Since miR193a-3p targets cyclin D1, a positive regulator of cell cycle, has tumor suppressive actions in various cancers, and its expression is reduced in BC, suggests that it may be effective in inhibiting BC growth." (PMID 36766731, 2023). "Indeed, there is a correlation between increased levels of cyclin D1 and the severity of the disease, such as tumor stage, lymph node involvement, and aggressiveness of OSCC." (PMID 38067304, 2023). "To assess the proliferation of the CT26 tumor cells, we examined their viability through the CCK8 kit, that measures mitochondrial activity in viable cells, as well as the gene expression of cyclin D1 or Ki67, which are associated with the cell cycle and cellular proliferation." (PMID 36979746, 2023). "The authors found that the cell cycle kinase CDK6 forms an active complex with the atypical cyclin I (CCNI) and that this complex promotes retinoblastoma phosphorylation, E2F‐mediated gene expression, and tumor proliferation in vitro and in vivo, similarly to the cyclin D1 (CCND1)/CDK6 complex." (PMID 37081792, 2023). "Indeed, miR-15/16 are known tumor suppressors, best characterized in B cell leukemia, which affect cell growth by restricting cell-cycle and anti-apoptotic genes such as Ccnd1 (cyclin D1), Bmi1, Bcl2, and Mcl1." (PMID 37862171, 2023). "Interestingly, numerous authors such as Bov, Miyamoto, Lam, and Huang have found an increase in cyclin D1 expression with a decrease in tumor differentiation, i.e., an increase in the histological grade of the tumor." (PMID 36982894, 2023). "PKM2-dependent histone H3 modifications are instrumental in epidermal growth factor (EGF)-induced expression of cyclin D1 and c-Myc, tumor cell proliferation, cell cycle progression, and brain tumorigenesis in its non-metabolic functions of histone modification." (PMID 37196116, 2023). "Finally, a cell cycle regulator has been described as another possible contributor to cisplatin resistance through the differential overexpression of CCND1 (Cyclin D1) in cisplatin-resistant tumor samples." (PMID 37175579, 2023). "Furthermore, the expression of EMT genes and oncogenes, including Mmp3, Mmp7, Mmp8, Fn1, Vim, Foxc2, Ctnnb1, Lgr5, Axin2, cMyc, Ccnd1, and Yap1, was significantly high in the tumor of cohoused Nlrp12–/– compared with WT mice." (PMID 37581937, 2023). "Similarly, in breast cancer, TLR5 activation in vitro inhibited tumor cell proliferation and colony formation by decreasing cyclin B1, cyclin D1 and cyclin E2 expression and increasing CDK inhibitor p27." (PMID 37112730, 2023). "Furthermore, our Western analysis on AKT pathway-associated gene expression in the NACC1-depleted tumor cells showed decreased expressions of phospho-PTEN, β-catenin, and cyclin-D1, which is consistent with the RNA-seq data." (PMID 37189841, 2023). "Moreover, the expression of a membrane-associated form of Ccnd1 harbouring the farnesylation signal of K-Ras (Ccnd1-CAAX) maximises the ability of tumour cells to invade and metastasize." (PMID 37684532, 2023). "Furthermore, combination treatment of DIM and 5-Fu induced β-catenin degradation and significantly reduced c-Myc and cyclin D1 levels compared with 5-Fu treatment alone in xenograft tumor tissues." (PMID 36785670, 2023). "Furthermore, nude mice injected with VDR-overexpressing SW480 cells revealed suppression of tumour growth and decreased expression of β-catenin, cyclin D1 and LEF-1." (PMID 37046222, 2023). "In a CDK-independent environment, inhibiting the DNA-binding activity of cyclin D1 and HDACs may interfere with gene expression, cell proliferation, and differentiation of tumor cells." (PMID 38086377, 2023). "In contrast previous studies have identified increased expression of CCND1 in tumor tissues." (PMID 37644520, 2023). "Similarly, a diet supplemented with 10% inulin was found to increase the tumor promotion explained by higher level of cytosolic β-catenin and higher expression of cyclin D1." (PMID 36819017, 2023).
tumor (continued). "Cyclin D1 has been proved to be upregulated in the GCs of GC tumour of the bone." (PMID 37509363, 2023). "Previously, it was reported that miR17-5p could repress RBL2, also named P130, to release activating transcription factor E2F4 or CTNNB1, which promoted tumor progression by inducing activation of multiple targeted genes like CCND1 and CCNE1 etc.." (PMID 37506248, 2023). "The SF-APSP micelles exhibited significant tumor suppressive effects, efficiently delivered SF to HepG2 cells through receptor-mediated endocytosis, and effectively inhibited the proliferation of cells by downregulating cyclin D1." (PMID 37175234, 2023). "In addition, Western blot and immunofluorescence were used to determine the protein expression changes in Bax, γH2AX and Cyclin D1 within the transplanted tumor tissues of nude mice." (PMID 37940975, 2023). "Moreover, it was showed that FIBP was also highly expressed in skin carcinogenesis and was involved in tumor cell cycle processes by regulating the key downstream target cyclin D1." (PMID 37310595, 2023). "A significant downregulation of cyclin D1 was detected in the tumor tissues of different treatment groups (EC/CuNPs, EC/R, and EC/CuNPs/R groups) by − 0.3, − 0.06, and − 0.6 folds, respectively, when compared with untreated tumor group." (PMID 36905557, 2023). "Subsequent analyses showed that EDX treatment suppressed the expression of STAT3, a transcription factor involved in tumor cell growth, cyclin D1, a cell cycle-related factor, and Ki67, a tumor growth rate marker, which were highly expressed in tumor tissues of Colon26-inoculated mice." (PMID 36751299, 2023). "There was a 37% reduction in tumor weight along with a significant decrease in staining for Ki67, CCND1, and E2F1; a significant increase in nuclear staining for cleaved caspase 3; and reduced staining for TGF-β3 and Masson’s trichrome in the tranilast treated mice." (PMID 37445642, 2023). "The molecular mechanism analysis suggested that PGG induced S-phase arrest by inhibiting DNA replication and induced G1-phase arrest by reducing the expression of cyclin D1, which, in turn, inhibited tumor growth in a triple-negative breast cancer xenograft model." (PMID 37375411, 2023). "The high expression of MACC1 and cyclin D1 was significantly correlated with tumor size." (PMID 35242498, 2022). "In recent years, there has been increasingly extensive exploration of the function of Wnt/β-catenin in the initiation and progression of different cancers, and cyclin D1 and c-myc, which are downstream targets of Wnt/β-catenin signaling, have been shown to affect tumor proliferation and metastasis." (PMID 35774359, 2022). "MACC1 binds to the positive feedback of the c-Met promoter region to activate the HGF/c-Met pathway, upregulates the expression of downstream target cyclin D1, and promotes tumor cell proliferation, invasion, metastasis, and epithelial mesenchymal transformation (EMT)." (PMID 35242498, 2022). "More precisely, the number of Cyclin D1 positive cells in the tumoral area was higher in the IH group compared to the N group (32.43 ± 2.93% versus 22.47 ± 2.9%, p = 0.0286); a trend was observed in the non-tumor area (2.85 ± 0.58% versus 1.42 ± 0.38%, p = 0.0562)." (PMID 35805134, 2022). "High levels of Cyclin-D1 are required to sustain tumor growth." (PMID 36292101, 2022).
tumor (continued). "The activation of the ERK signaling pathway may stimulate tumor cell proliferation through its ability to initiate the expression of crucial growth-stimulating genes, such as cyclin D1 and early growth response-1 (EGR-1)." (PMID 35764974, 2022). "RPLP0 interacts with GCIP to activate cyclin D1, thereby promoting tumor cell proliferation." (PMID 35974014, 2022). "In papillomavirus-induced tumors, Cyclin D1’s role is less clear and in particular, in animal species with papillomavirus-associated neoplasms, its role in tumorigenesis is not known." (PMID 36136690, 2022). "In addition, radotinib repressed expression of the activity and expression of STAT3, and its downstream proteins including Bcl-xL, Mcl-1, c-Myc, cyclin D1, and cyclin D3 in IM-9 cells isolated from the tumor tissue." (PMID 35503759, 2022). "Moreover, this tumour model lacks expression of the oestrogen and progesterone receptor and overexpresses EbrB2 and cyclin D1 as the tumour progresses, which mimics human breast cancers with poor prognosis." (PMID 35808806, 2022). "MiR-326 is considered to be a tumor suppressor in several human cancers, since it could directly target downstream oncogenes, such as cyclin D1, phox2a, and Notch1." (PMID 35012553, 2022). "Furthermore, the changes in apoptosis-related proteins and cell cycle-associated proteins, including PUMA, Bcl-2, Bax, Caspase-9, p21, and Cyclin D1, in the tumor tissues were consistent with the in vitro results." (PMID 35759135, 2022). "SOX6 reduces tumor cell proliferation by promoting the expression of P21 and inhibiting CyClin D1." (PMID 35252180, 2022). "Cyclin D1 (CCND1) serves as a central regulator for cell cycle progression, and its overexpression results in dysregulated cyclin-dependent kinases activity, rapid cell growth under conditions of restricted mitogenic signaling, and ultimately, tumor growth." (PMID 36075937, 2022). "Moreover, we used immunohistochemistry (IHC) to evaluate the expression levels of c-fos, CDK6, and cyclin D1 in the tumor tissues." (PMID 35444864, 2022). "Also, we found downregulating CCND1 mitigated pro-tumor effects mediated by CDC42EP3 overexpression." (PMID 35365622, 2022). "Specifically, CDC42EP3 may perform a function through regulating c-Myc-mediated transcription of CCND1 in both experimental cell lines and tumor-promoting effects were significantly suppressed following knockdown of CCND1 in U251 cells." (PMID 35365622, 2022). "In addition to the CCND1 amplification seen in the cell line, CNAs involving CCND1 were observed in four cases in which three tumors displayed a small focal gain and one tumor a large 11q gain." (PMID 35859155, 2022). "Likewise, prostate-specific deletion of Tubb4a reduces spontaneous tumor growth and metastasis via inhibition of NF-κB, cyclin D1, and c-MYC signaling activation." (PMID 35589707, 2022). "Furthermore, relative protein levels of cyclin E and cyclin D1 in tumor tissues were inhibited by KPNB1 silencing but enhanced by KPNB1 overexpression." (PMID 35902727, 2022). "Clinically, cyclin D1 expression is correlated with tumor size, invasion, metastasis and clinical stages, highlighting that cyclin D1 can be considered as a prognostic factor to evaluate patient prognosis, and cyclin D1 signaling can be targeted to treat human cancers." (PMID 35565262, 2022). "Furthermore, CAFs-Exo remarkably increased miR-1290, β-catenin, c-Myc and Cyclin D1 level and reduced GSK3β level in tumor tissues; however, these phenomena were all reversed by anti-miR-1290 treatment." (PMID 35999213, 2022). "Moreover, the administration of XHA suppresses tumor proliferation by downregulating the levels c-Myc, and Cyclin D1 and Ki-67 besides inducing Caspase-3-mediated apoptosis in AOM-induced Sprague-Dawley rats." (PMID 35053565, 2022).
tumor (continued). "In addition, overexpression of CD44 upregulates the expression of cyclin D1 through the activation of ERK pathway that will promote tumour proliferation and migration of BC, ovarian cancer, and squamous cell carcinoma." (PMID 36505828, 2022). "Cyclin D1 is a regulator of the progression of cells into the proliferation stage of the cell cycle, in LNCaP cells cyclin D1 overexpression enhancing S-phase entry, increasing colony formation and the tumour growth rate." (PMID 35204839, 2022). "Interestingly, our study showed that CxPA that developed after a preceding recurrent tumor (six tumors out of 15) showed moderate or high nuclear cyclin D1 expression compared with other CxPAs." (PMID 35637257, 2022). "A statin hydroxamate synthesized by Tzu-Tang Wei prevented CAC in a mouse model by decreasing the infiltration of macrophages and neutrophils in the tumor-surrounding regions, and by reducing the inflammatory cytokines, chemokines and cyclin D1 in the tumor tissues." (PMID 36230676, 2022). "In addition to pro-angiogenic mediators, STAT3 also upregulates cyclin D1 and Bcl-2, resulting in rapid tumor growth through increased cell-cycle progression and reduced cell death." (PMID 36046049, 2022). "Furthermore, the downregulation of cyclin D1 expression in tumor tissues revealed that the cell cycle was obstructed to inhibit cell proliferation by SOL." (PMID 36506573, 2022). "In addition, epigallocatechin-3-gallate can inhibit cell proliferation and the formation of oncospheres enriched with tumor stem cells at 40 μM by downregulating the levels of Axin2, c-Myc, and Cyclin D1 and PCNA." (PMID 35053565, 2022). "Therefore, the expression levels of relevant genes were measured; the result showed that FoxO1 was significantly upregulated, while Cyclin D1 was significantly downregulated after mitochondrial inhibition in tumor cells." (PMID 35865479, 2022). "Cyclin D1 and mitochondrial complex IV were detected in tumor samples from PTC patients with LNM." (PMID 35865479, 2022). "The results showed that the protein expression levels of β-catenin, TCF4 and cyclin D1 in the tumor-adjacent tissues were significantly lower than those in the normal tissues, suggesting that ALV-J inhibited cell growth and development by decreasing the Wnt/β-catenin signaling pathway." (PMID 36461084, 2022). "The prognostic value of high CCND1 copy number in BC tumours remains unresolved." (PMID 35459982, 2022). "Therefore, increased expression of Cyclin D1 plays a decisive role in tumor formation and the maintaining of the malignant phenotype." (PMID 35626215, 2022). "Besides, results of IHC assay also indicated that KLF13 obviously inhibited Ki67 expression, along with down-regulating the protein expressions of β-catenin and its downstream Cyclin D1 and c-Myc in tumor tissues." (PMID 36336731, 2022). "In addition, we also found that Ki67, IRS2 and CCND1 protein were upregulated in tumor tissues by an immune-fluorescence assay, which is consistent with the observations in vitro." (PMID 35844799, 2022). "As a transcription factor, STAT3 could promote growth and inhibit apoptosis of tumor cells by mediating transcription of downstream target genes, especially cyclin D1." (PMID 36157053, 2022). "EEF1A1 can promote tumor spread through the STAT1-cyclin D1 pathway." (PMID 35126520, 2022). "Furthermore, there is a lack of clarity regarding the regulation of mitochondrial respiration in PTC tumor progression through the PI3K/Akt/FoxO1/Cyclin D1 pathway." (PMID 35865479, 2022). "Indeed, AM is clinically characterized as a slow growing tumor, even though the present study showed the higher expression of Ki67 and Cyclin D1 was shown in the present study." (PMID 36057617, 2022). "Cyclin D1 is highly expressed and promotes tumorigenesis in numerous tumours." (PMID 35255935, 2022).